POSTN (periostin)
Diseases named in the same sentence as POSTN in open-access papers (continued):
Sharing a sentence is not in itself a finding about the gene and the disease.
glioma (continued). "Because it is a potent HIF inhibitor, we were interested to determine whether ACF could block the increased expression of POSTN, M-CSFR and TGF-β and further inhibit the hypoxia-induced recruitment and M2-polarizing effects of TAMs in gliomas." (PMID 27602954, 2016). "Besides, a recent study showed that glioma-derived kynurenine activates the aryl hydrocarbon receptor (AHR) in TAMs, modulating their recruitment and inducing T-cell dysfunction, while glioma stem cell-derived POSTN recruits TAMs." (PMID 41353343, 2025). "The predictive model constructed using four genes involved in macrophages and cancer cells, namely POSTN, CHI3L1, SAA1, and MMP9, holds promise in distinguishing high inflammation-hypoxia-immunosuppression microenvironment signatures and helps optimize trametinib selection for glioma treatment." (PMID 39574472, 2024). "Moreover, our study revealed that the expression levels of four genes (POSTN, CHI3L1, SAA1, and MMP9) were significantly elevated in glioma samples obtained from patients who experienced recurrence within one year after TMZ treatment, along with an increased risk score." (PMID 39574472, 2024). "Moreover, among glioma tissues, GBM tissues presented the highest expression of POSTN." (PMID 39227950, 2024). "However, in the glioma specimens, as the level of HIF-1α expression increased, we observed a corresponding increase in the number of POSTN+ cells in non-stem glioma cells (NSGCs) (CD133-)." (PMID 27602954, 2016). "However, an increase in the production of POSTN and a more diffuse distribution of POSTN were observed in both perivascular and non-vascular areas in the high HIF-1α expressing glioma specimens." (PMID 27602954, 2016).
pulmonary fibrosis (60 papers, 2012 to 2025). Chronic progressive interstitial lung disorder characterized by the replacement of the lung tissue by connective tissue, leading to progressive dyspnea, respiratory failure, or right heart failure. "For example, POSTN is highly expressed in fibroblasts from patients with pulmonary fibrosis, and POSTN-deficient mice exhibit resistance to bleomycin-induced pulmonary fibrosis." (PMID 39989459, 2025). "In the context of activation in pulmonary fibrosis, periostin expression is also associated to persistent airway obstruction (FEV1/vital capacity [VC] < 88%)." (PMID 40980110, 2023). "Elevated serum periostin is associated with disease progression and the severity of pulmonary fibrosis, colorectal cancer and systemic sclerosis." (PMID 32947957, 2020). "Other studies have implicated periostin in murine models of lung fibrosis, where it has been shown to induce chemokines to recruit neutrophils and macrophages." (PMID 24647608, 2014). "Increased periostin expression is associated with skin and lung fibrosis." (PMID 34571811, 2021). "This is one underlying mechanism by which periostin causes pulmonary fibrosis." (PMID 32000779, 2020). "Furthermore, periostin has been linked with development of fibrosis in the pathogenesis of idiopathic interstitial pneumonia, and idiopathic pulmonary fibrosis (IPF)." (PMID 24146092, 2014). "Moreover, we and another group have shown that a genetic deficiency of periostin or the administration of neutralizing antibodies (Abs) against periostin protected mice from bleomycin (BLM)-induced pulmonary fibrosis, suggesting the significance of periostin in generating pulmonary fibrosis." (PMID 32000779, 2020). "POSTN in fibroblasts is involved in cross-talk with TGF-β and is implicated in the pathogenesis of pulmonary fibrosis." (PMID 40269953, 2025). "Another research evaluated small interfering RNA or antisense oligonucleotide against periostin can inhibit lung fibrosis efficently by direct administration into the lung by intranasal route." (PMID 38370408, 2024). "In summary, there is a clear association between POSTN and IPF, and inhibiting POSTN shows promise as a treatment for lung fibrosis." (PMID 38370408, 2024). "CALD1, CDH2, and POSTN, identified as potential contributors to pulmonary fibrosis, present promising therapeutic targets for IPF patients." (PMID 38370408, 2024). "Upon discovering the elevated expression of CALD1, CDH2, and POSTN in pulmonary fibrosis, we designed two pairs of siRNA for each gene to effectively knockdown their expression in HLFs." (PMID 38370408, 2024). "Two studies have shown that elevated levels of periostin in the serum and plasma of patients with idiopathic pulmonary fibrosis predicted decreased lung function after 6 months and 48 weeks, respectively." (PMID 39534447, 2024). "It has elsewhere been reported that Tgf-β1 works downstream of periostin, whilst cross-talk between Tgf-β1 and periostin has been seen as an amplifying mechanism for pulmonary fibrosis." (PMID 38255321, 2024). "Within this intersection, three hub genes, CALD1, CDH2, and POSTN, were found to be dysregulated and potentially significant in the context of pulmonary fibrosis." (PMID 38370408, 2024). "Their results showed significant reduction in lung tissue periostin levels, collagen deposition, and lung fibrosis score, showing promise for future potential CRS treatment modalities." (PMID 36832203, 2023). "This study investigated the utility of periostin, a matricellular protein, as a prognostic biomarker in patients with idiopathic pulmonary fibrosis (IPF) who received nintedanib." (PMID 38151520, 2023). "The role of periostin in SSc is controversial with respect to its pathophysiologic implications in skin and pulmonary fibrosis." (PMID 36369212, 2022).
pulmonary fibrosis (continued). "Serum levels of periostin in idiopathic pulmonary fibrosis are significantly high, correlating with the disease severity, suggesting periostin as a predictive biomarker of lung fibrosis." (PMID 35707463, 2022). "Periostin furthered the recruitment of neutrophils and macrophages or myofibroblasts differentiation, accelerating pulmonary fibrosis." (PMID 36611844, 2022). "One study suggests that POSTN promotes idiopathic pulmonary fibrosis through mesenchymal effects, cross-linking collagen and stiffening the matrix created by fibroblasts, thereby activating cells for further production of the extracellular matrix." (PMID 36409751, 2022). "In areas of ongoing fibrosis in lung tissues from idiopathic pulmonary fibrosis patients or in the lungs of asthmatic patienta, periostin is highly expressed, contributing to airway fibrosis and remodeling." (PMID 35707463, 2022). "Periostin secreted by recruited fibrocytes augments myofibroblast differentiation and lung fibrosis." (PMID 35707463, 2022). "We focused on the NF-κB pathway since we and other investigators have previously demonstrated that NF-κB activation promotes periostin expression in glomerulonephritis and also in a model of pulmonary fibrosis, respectively described." (PMID 35883655, 2022). "The siRNA and antisense oligonucleotide targeting periostin, OC-20, and antibodies targeting αv integrin prevented lung fibrosis." (PMID 36611844, 2022). "We first summarise the importance of type 2 biomarker and then describe the pathological role of periostin in the development and progression of type 2 allergic inflammation and pulmonary fibrosis." (PMID 34439751, 2021). "In this article, we focus on allergic diseases and pulmonary fibrosis, for which we and others are now developing detection systems for periostin as a biomarker." (PMID 34439751, 2021). "In pulmonary fibrosis, it is reported that periostin is involved cross-talk with TGF-β, generating the expression of TGF-β downstream effector molecules involved in the pathogenesis of the disease." (PMID 34439751, 2021). "Neutralization of IL-13 or IFN-γ during Ag plus IL-18 challenges inhibited the combination of eosinophilic infiltration, lung fibrosis, and periostin deposition or the combination of neutrophilic infiltration and airway hyperresponsiveness, respectively." (PMID 34367377, 2021). "Periostin is a matricellular protein that regulates cell function and plays a pivotal role in the pathogenesis of allergic inflammation [17.32] and pulmonary fibrosis." (PMID 34439751, 2021). "We were particularly interested in the ECM associated genes and selected COL4A1, POSTN, MMP1 and MMP3 since they have been previously shown to be associated with pulmonary fibrosis." (PMID 33905434, 2021). "Periostin seems to play a critical role in the pathogenesis of pulmonary fibrosis, and thus offers a promising therapeutic target for IPF." (PMID 34702952, 2021). "Earlier research displayed that POSTN can promote myofibroblast differentiation and type I collagen production, contributing to aberrant lung fibrosis." (PMID 34476240, 2021). "On the other hand, periostin, was shown to play a vital role in chemokines induction to recruit neutrophils and macrophages that participate in pulmonary fibrosis in mouse model." (PMID 33195308, 2020). "Cluster 2 cells showed increased expression of POSTN and COL1A1 and other extracellular matrix genes implicated in pulmonary fibrosis." (PMID 33257409, 2020). "Periostin is a matricellular protein playing a critical role in the pathogenesis of pulmonary fibrosis." (PMID 32000779, 2020). "Given that periostin is a key molecule in the pathogenesis of pulmonary fibrosis, it is a promising therapeutic target for IPF." (PMID 32000779, 2020). "In contrast, myofibroblasts are likely to be the main periostin-producing cells in pulmonary fibrosis." (PMID 28355256, 2017).
pulmonary fibrosis (continued). "Periostin was chosen to be analyzed alongside semaphorin-7A due to its essential role in myofibroblast differentiation, tissue remodeling, and lung fibrosis, and due to its high increased expression level in semaphorin-7A-siRNA-treated HLF." (PMID 28095470, 2017). "To evaluate the anti-inflammatory and anti-fibrotic effects of CNP against BLM-induced lung fibrosis in periostin-CNP Tg mice, we analyzed the mRNA expression changes of IL-1β, IL-6, bFGF, TGF-β, TIMP1, and collagen 1A." (PMID 26895702, 2016). "The results indicate that CNP produced anti-inflammatory and anti-fibrotic effects in the BLM-induced pulmonary fibrosis model in periostin-CNP Tg mice." (PMID 26895702, 2016). "We examined the in vivo anti-fibrotic effect of CNP via lung fibroblasts by using periostin-CNP Tg mice in the BLM-induced lung fibrosis model." (PMID 26895702, 2016). "Neutralization of IL-13 during the Ag plus IL-18 challenges inhibited eosinophilic infiltration, lung fibrosis, and periostin deposition; while neutralization of IFN-γ during the Ag plus IL-18 challenges inhibited neutrophilic infiltration and AHR." (PMID 25981515, 2015). "It has been suggested that periostin acts as an inducer of chemokines in the inflammatory response pivotal for the process of pulmonary fibrosis." (PMID 24146092, 2014). "The neutralization of IFN-γ during antigen challenge with antigen plus IL-18 inhibited both lung fibrosis and periostin deposition and both neutrophilic infiltration and airway hyperresponsiveness, respectively." (PMID 23300949, 2013). "In bleomycin-induced lung fibrosis in mice, Periostin antibodies were able to prolong survival." (PMID 39940700, 2025). "Whether POSTN exhibits certain post-transcriptional regulatory mechanisms in pulmonary fibrosis remains to be investigated." (PMID 38370408, 2024). "Notably, the expressions of periostin, fibronectin, and Col1a1 were significantly reduced in rs35705950 TG mice with lung fibrosis relative to their WT counterparts." (PMID 39329706, 2024). "Consistently, in lung tissue, periostin is highly expressed in patients with pulmonary fibrosis." (PMID 37549960, 2023). "The evaluation of periostin as a lung fibrosis biomarker in combination with HRCT examination may contribute to deciding therapeutic strategies for RA-ILD patients whom it is difficult to classify by radiological ILD patterns." (PMID 38002712, 2023). "The evaluation of periostin as a lung fibrosis biomarker in combination with HRCT examination may contribute to deciding therapeutic strategies for RA-ILD patients." (PMID 38002712, 2023). "Previous studies suggest that periostin may play a critical role in the pathogenesis of pulmonary fibrosis and may serve as a biomarker of disease activity and progression in IPF." (PMID 36369212, 2022). "Given the important roles that periostin may play in lung fibrosis, we sought to further explore its expression in relationship with SSc-ILD." (PMID 36369212, 2022). "Periostin, induced by the Th2 cytokines IL-4 and IL-13, has been reported to be involved in pulmonary fibrosis with crosstalk of transforming growth factor-β21,22, and serum periostin could be a good predictor of decreased lung function and poor prognosis." (PMID 36380088, 2022). "Periostin is overexpressed in the lungs of patients with idiopathic pulmonary fibrosis (IPF)." (PMID 36611844, 2022). "Because periostin is easily secreted and can be detected noninvasively in biological fluids, its utility as a biomarker has been investigated in various diseases, including SSc, idiopathic pulmonary fibrosis (IPF), asthma, and cancer." (PMID 36369212, 2022). "Therefore, although periostin has been implicated in various pathogeneses, we will focus on allergic diseases and pulmonary fibrosis, for which we and others are now developing detection systems for periostin as a biomarker, in this article." (PMID 34439751, 2021).
pulmonary fibrosis (continued). "Moreover, we have recently found that cross-talk between TGF-β, a critical mediator for pulmonary fibrosis, and periostin via αVβ3 integrin is important for generating pulmonary fibrosis." (PMID 32000779, 2020). "Building on this concept, we have recently found that cross-talk between TGF-β and periostin is important for the generation of pulmonary fibrosis and that CP4715, a potent inhibitor of integrin αVβ3, improves pulmonary fibrosis in mice by inhibiting TGF-β signaling." (PMID 32000779, 2020). "On the other hand, periostin is involved in different pathological processes such as lung fibrosis." (PMID 32492951, 2020). "Periostin expression is observed in the fibroblastic foci and adjacent to α-smooth muscle actin—positive myofibroblasts, suggesting that these are the main periostin-producing cells in pulmonary fibrosis." (PMID 28355256, 2017). "In agreement with our results, neutralization of IFN-γ during challenge with antigen plus IL-18 inhibited the combination of eoainophilic infiltration, lung fibrosis, and periostin deposition or the combination of neutrophilic infiltration and airway hyperresponsiveness, respectively." (PMID 22567105, 2012). "Biomarkers previously associated with pathobiology and/or progression in pulmonary fibrosis were selected to reflect cellular senescence (telomere length), pulmonary epithelium (SP-D, RAGE), myeloid activation (CXCL13, YKL40, CCL18, OPN) and fibroblast activation (POSTN, COMP, PROC3)." (PMID 38753183, 2024). "Since periostin may contribute to fibrosis, our study may provide a rationale to inhibit periostin expression in alveolar epithelium under diseased conditions such as pulmonary fibrosis." (PMID 29672593, 2018). "Thus, periostin is a key player in the pathogenesis of pulmonary fibrosis." (PMID 28355256, 2017). "Periostin has been found to be related to the physiopathology of multiple diseases such as: ankylosing spondylitis (AS), idiopathic interstitial pneumonias (IIPs), idiopathic pulmonary fibrosis (IPF), renal inflammation and fibrosis, heart aging, cancer, and allergic diseases." (PMID 25981515, 2015). "The crosstalk between periostin and TGF-β is established to be critical for amplifying the downstream signaling pathways in pulmonary fibrosis." (PMID 41148799, 2025). "Recent research shows that periostin enhances the TGF-β/Smad2/3 signaling pathway via integrin αVβ3/αVβ5 in lung fibroblasts, contributing to pulmonary fibrosis development." (PMID 38370408, 2024). "The relative mRNA expressions of periostin, fibronectin, collagen type I alpha 1 (Col1a1), and alpha-smooth muscle actin (α-SMA) were significantly elevated in both WT and TG mice with lung fibrosis compared to their respective saline-treated controls." (PMID 39329706, 2024). "In pulmonary fibrosis, LOXL 2 promotes fibrogenesis through periostin signaling, independently of the TGF-β pathway." (PMID 36499287, 2022). "Periostin is a matricellular protein highly expressed in the lung tissues of IPF patients, playing a critical role in the pathogenesis of pulmonary fibrosis." (PMID 32000779, 2020). "We show that BLM-induced pulmonary fibrosis is attenuated in both CNP-treated mice and periostin-CNP Tg mice by the CTP downregulating pro-inflammatory and pro-fibrotic cytokines and inhibiting collagen deposition." (PMID 26895702, 2016). "Additionally, other identified biomarkers such as BPI fold containing family B member 1 and periostin, the levels of which were increased in serum EVs in PPF, have been reported to be involved in the pathogenesis of pulmonary fibrosis." (PMID 38855869, 2024). "Additionally, it has been reported that treatment of antibodies (OC-20) against periostin effectively improved the fibrotic progression and prognosis in mouse models of bleomycin (BLM)-induced pulmonary fibrosis." (PMID 38370408, 2024).
pulmonary fibrosis (continued). "Furthermore, knockdown of CALD1, CDH2, and POSTN led to a reduction in TGF-β1-induced fibrotic markers, suggesting their potential roles in the development of pulmonary fibrosis." (PMID 38370408, 2024). "Taken together, the elevated levels of POSTN, THBS2, COL6A1, and LOXL1 may contribute to the development of pulmonary fibrosis, similar to what is seen in IPF, thus connecting fibrosis to inflammation in DM-ILD." (PMID 37928522, 2023). "Mice with BLM-induced lung fibrosis receiving intratracheal corisin showed a significantly increased BALF total number of lymphocytes and enhanced BALF levels of MUC-1, periostin, osteopontin, and collagen I compared to counterpart mice receiving intratracheal scrambled peptide." (PMID 35322016, 2022). "The POSTN and TGF-β levels were estimated to check whether AEO had an effect on the regression of lung fibrosis in OVA+PM10-induced mice." (PMID 35335934, 2022). "There have been numerous reports that the crosstalk between TGF-β and periostin leads to pulmonary fibrosis and inhibitors for integrin αvβ3, a periostin receptor can block pulmonary fibrosis in animal model and TGF-β signaling in lung fibrosis." (PMID 35707463, 2022). "However, our group found an increase in serum biomarkers of pulmonary fibrosis (MMP7, MMP1, and periostin) in patients with early fibrotic changes in chest CT at 2 months after hospital discharge, not only in IMV patients but also in those treated with conventional or high flow nasal cannula oxygen." (PMID 36096801, 2022). "As there is no published evidence showing perisotin expression by ATII cells in IPF patients, it would be important to compare periostin and eotaxin expression levels in alveolar and airway epithelial cells isolated from lungs of patients with or without pulmonary fibrosis." (PMID 29672593, 2018). "In addition, as the combination of CCL17 and total POSTN showed excellent performance for predicting non-IPF-ILD progression in the discovery cohort, developing a combination of multiple biomarkers is expected to more accurately determine the complex pathogenesis of pulmonary fibrosis." (PMID 40269953, 2025).